MEF2D (myocyte enhancer factor 2D)
Diseases named in the same sentence as MEF2D in open-access papers (continued):
Sharing a sentence is not in itself a finding about the gene and the disease.
rhabdomyosarcoma (5 papers, 2013 to 2024). A rare aggressive malignant mesenchymal neoplasm arising from skeletal muscle. "In contrast, MEF2D was recently identified as a TSG in rhabdomyosarcoma and low-grade uterine leiomyosarcomas, thus suggesting that MEF2D plays a cell-type-specific role in cancer cells." (PMID 38791246, 2024). "In agreement with our observation, a recent study demonstrated that expression of exogenous MEF2D inhibited cell proliferation and anchorage-independent growth in rhabdomyosarcoma cell lines." (PMID 30514247, 2018). "MEF2D also acts as tumor suppressor in liposarcoma, leiomyosarcoma and rhabdomyosarcoma through promotion of cell proliferation and anchorage independent growth and inhibition of differentiation." (PMID 28340574, 2017). "The expression of exogenous MEF2D in rhabdomyosarcoma cell lines promoted differentiation and inhibited cell proliferation, anchorage independent-growth and cell migration." (PMID 26506234, 2016). "In rhabdomyosarcoma cells compared to normal myoblasts, MEF2D expression tended to be lost and a less active isoform of MEF2C tended to be expressed." (PMID 26506234, 2016). "MEF2C and MEF2D may also act as tumor suppressors in rhabdomyosarcoma." (PMID 26506234, 2016).
B-cell acute lymphoblastic leukemia (4 papers, 2017 to 2022). A neoplasm of lymphoblasts committed to the B-cell lineage, typically composed of small to medium-sized blast cells. "Recently, fusion genes involving MEF2D have been identified in the precursor B-cell acute lymphoblastic leukemia, suggesting a potential connection between TEX41 and MEF2D." (PMID 34233751, 2021). "Specifically, SS18 rearrangements involving the MEF2C and MEF2D partner genes, resulting in MEF2C::SS18 and MEF2D:SS18 gene fusions, have been identified in microsecretory adenocarcinoma and the B‐cell acute lymphoblastic leukemia, respectively." (PMID 35639915, 2022).
cardiomyopathies (3 papers, 2021 to 2024). "Dysregulation of Mef2D expression or activity is associated with various muscle-related disorders, including muscular dystrophies and cardiomyopathies." (PMID 39637238, 2024).
gallbladder carcinoma (3 papers, 2021 to 2022). "In gallbladder cancer, miR-335 suppresses the myocyte enhancer factor-2D (MEF2D) and improves cell proliferation as well as increasing the sensitivity of cancer cells to 5-fluorouracil chemotherapy." (PMID 35651814, 2022). "MiR-335 by targeting MEF2D could inhibit cell growth and sensitize gallbladder carcinoma cells to 5-FU." (PMID 33954114, 2021).
melanoma (3 papers, 2019 to 2025). A malignant, usually aggressive tumor composed of atypical, neoplastic melanocytes. "In addition, the knockdown of MEF2D displayed a marginal effect on PD-L1 expression in SIRT7-overexpressed melanoma cells under TG treatment." (PMID 36918544, 2023). "Therefore, the regulation of PD-L1 by SIRT7 is independent of MEF2D, and the regulatory mechanism of MEF2D by SIRT7 does not exist in melanoma cells under ER stress." (PMID 36918544, 2023).
type 2 diabetes (3 papers, 2025 to 2026). "A recent study showed that glucose-induced alternative splicing of MEF2D is connected to the chronic inflammation in type 2 diabetes." (PMID 41465472, 2025).
adenocarcinoma of the lung (2 papers, 2017 to 2023). "According to immunohistochemical score, MEF2D expression level in lung adenocarcinoma tissues was correlated with tumor differentiation, N stage, M stage and intrapulmonary metastasis (P<0.05)." (PMID 37653017, 2023). "In a previous study, MEF2D was demonstrated to enhance the proliferation and metastasis of lung adenocarcinoma cells A549 and H1299 by promoting the transcription of NUSAP1." (PMID 37653017, 2023). "ZDHHC5 was previously seen involved in neoplasia with different partners: a ZDHHC5-SMTNL1 fusion was found in SCC of the ovary, a CTNND1-ZDHHC5 in adenocarcinoma of the lung, ZDHHC5-LCT in adenocarcinoma of the breast, and MEF2D-ZDHHC5 in grade III-IV astrocytoma of the brain." (PMID 28186972, 2017).
amyotrophic lateral sclerosis (2 papers, 2017 to 2018). Amyotrophic lateral sclerosis (ALS) is a neurodegenerative disease characterized by progressive muscular paralysis reflecting degeneration of motor neurons in the primary motor cortex, corticospinal tracts, brainstem and spinal cord. "Moreover, disruption of Mef2d andMef2c pathways has been linked to amyotrophic lateral sclerosis, and aberrantactivation was shown to mediate neuronal death in mouse and fly models of Friedreichataxia, indicating their potential role inneurodegeneration." (PMID 30517858, 2018). "A recent study showed a significant up-regulation of MEF2C and MEF2D mRNA levels in both sporadic and SOD1+ amyotrophic lateral sclerosis (ALS) patients detected by gene expression analysis, and a down-regulation of their targets, BDNF, KLF6, and RUFY3." (PMID 29340119, 2017).
autism spectrum disorder (2 papers, 2022 to 2024). A spectrum of developmental disorders that includes autism, and Asperger syndrome. "Mef2d gene disruption could be a risk factor for multiple neurodevelopmental disorders and mental illnesses, such as autism spectrum disorders, intellectual disability and schizophrenia." (PMID 35875662, 2022). "Similarly, conditional deletion of MEF2C, but not MEF2A and MEF2D, is linked with altered memory formation and synaptic plasticity in the hippocampus, and MEF2C-related aberrations have been implicated in the development of autism-spectrum disorders (ASDs)." (PMID 38796067, 2024).
Autoimmunity (2 papers, 2019 to 2024). The occurrence of an immune reaction against the organism's own cells or tissues. "The lack of spontaneous inflammation or autoimmunity in Ikzf1-fl-Foxp3-Cre mice is similar to mice with Treg-specific deletion of Prdm1, Icos, Il10 and Mef2d." (PMID 38655862, 2024).
Diabetes (2 papers, 2023 to 2024). "To determine whether this applies to our CMECs and whether the observed dysregulation of KLF expression in diabetes is linked to the observed MEF2D dysregulation in our diabetic models, we knocked down MEF2A or MEF2D in nondiabetic HCMECs and analyzed KLF2 and KLF4 gene expression." (PMID 36768805, 2023). "We show that both KLFs 2 and 4, as well as MEF2D, are dysregulated in human and porcine models of diabetes." (PMID 36768805, 2023). "We also describe, for the first time, a role for myocyte enhancer factor 2D (MEF2D) in cardiac microvascular dysfunction in diabetes." (PMID 36768805, 2023). "Moreover, we established a link between our previously reported overexpression of miR-92a in diabetes and dysregulated MEF2D levels, which we have shown here in both diabetic HCMECs and diabetic porcine ventricular tissue samples (Graphical Summary)." (PMID 36768805, 2023).
dilated cardiomyopathy (2 papers, 2022 to 2025). Cardiomyopathy which is characterized by dilation and contractile dysfunction of the left and right ventricles. "Rbfox1 also regulates splicing of a MEF2A exon in mouse and zebrafish heart that is mis-spliced in cells from human patients with dilated cardiomyopathy, and Rbfox1 and Rbfox2 cooperatively regulate splicing of Mef2D during C2C12 differentiation." (PMID 34996845, 2022).
dopaminergic neuroblastoma (2 papers, 2013 to 2025). A neuroblastoma associated with increased dopamine excretion. "NH4Cl inhibited lysosome-mediated degradation, resulting in the cytosolic buildup of α-synuclein and myocyte enhancer factor 2D (MEF2D) proteins in a human dopaminergic neuroblastoma SH-SY5Y cell line." (PMID 40650243, 2025).
epilepsy (2 papers, 2016 to 2022). A brain disorder characterized by episodes of abnormally increased neuronal discharge resulting in transient episodes of sensory or motor neurological dysfunction, or psychic dysfunction. "Here, we found enrichment for binding sites of ARNTL, important for circadian rhythm associated with BD, MEF2D, involved in neuronal differentiation and PD, and MEF2C, involved in ASD, ID, and epilepsy among others." (PMID 27014338, 2016).
leiomyosarcoma (2 papers, 2017 to 2022). An uncommon, aggressive malignant smooth muscle neoplasm, usually occurring in post-menopausal women. "Interestingly, it has been described that MEF2D binds to the promoter and regulates the expression of Hdac9 during muscle differentiation, and in leiomyosarcoma cells." (PMID 35076395, 2022).
lupus (2 papers, 2022 to 2025). "Indeed, most Nr4a1-controlling genes (Grin1, Creb3l3, Mef2a, Mef2c, and Mef2d) were reduced in the lupus hippocampus, as revealed by sequencing assays." (PMID 35177587, 2022).
lymphoma (2 papers, 2011 to 2019). A malignant (clonal) proliferation of B- lymphocytes or T- lymphocytes which involves the lymph nodes, bone marrow and/or extranodal sites. "Indeed, the binding of myocyte enhancer factor 2D to Zp recruits class II histone deacetylases (HDACs), which presumably promote a repressed chromatin structure on Zp in lymphoma cell lines." (PMID 20980528, 2011).
malignant rhabdoid tumor (2 papers, 2014 to 2020). "In particular, in malignant rhabdoid tumor cell lines, increased binding of epigenetic silencers HDAC9 and MEF2D at SMARCA2 promoter sites has been associated with such heterozygous polymorphisms." (PMID 32575483, 2020).
myxoma (2 papers, 2019 to 2022). A benign soft tissue neoplasm characterized by the presence of spindle and stellate cells, lobulated growth pattern, and myxoid stroma formation. "The clinical results of the experiment confirmed that miR-122-dependent downregulation of MEF2D by PPARg suppresses the proliferation of myxoma cells, suggesting that PPARg may exert its antiproliferative effects by negatively regulating the MEF2D." (PMID 35328730, 2022). "Similar studies reveal that MEF-2D expression positively correlates with the proliferation of CM cells; MEF-2D expression can be suppressed by miR-218, a tumor suppressor which is downregulated in myxoma cells and serves as an important target for treatment of cardiac myxoma." (PMID 31105874, 2019).
non-small cell lung carcinoma (2 papers, 2017 to 2019). A group of at least three distinct histological types of lung cancer, including non-small cell squamous cell carcinoma, adenocarcinoma, and large cell carcinoma. "Bioinformatics analyses of the 16 enrolled GSE datasets from Gene Expression Omnibus online database showed myocyte enhancer factor 2D (MEF2D) level significantly increased in COPD patients coexisting non-small-cell lung carcinoma (NSCLC)." (PMID 28340574, 2017).
sarcoidosis (2 papers, 2020 to 2022). Sarcoidosis is a multisystemic disorder of unknown cause characterized by the formation of immune granulomas in involved organs. "Interestingly, both DBR1 and MEF2D are target antigens of natural autoAbs of sarcoidosis." (PMID 32046322, 2020). "Because sarcoidosis is a granulomatous disease, we found autoAbs against macrophage-associated antigens, including major facilitator superfamily domain containing 6 (MFSD6) and myocyte enhancer factor 2D (MEF2D) in our analysis of serum autoAbs from patients with a definite diagnosis of sarcoidosis." (PMID 32046322, 2020).
atherosclerosis (1 paper, 2023). A disease characterized by the build-up of fatty material and calcium deposition in the arterial wall resulting in partial or complete occlusion of the arterial lumen. "In addition, genes predicted to be targeted by the miR-17-5p, not previously associated with atherosclerosis, include ARID4B, E2F, GATA1, MEF2D, NR1I2, PURA, and RBL2." (PMID 36859458, 2023).
Blindness (1 paper, 2019). Blindness is the condition of lacking visual perception defined as a profound reduction in visual perception. "Preliminary studies of MEF-2d-null mice indicated that these mice exhibited normal viability and life span, but heterozygous alleles of MEF-2c mouse showed debilitating effects in bone differentiation, and MEF-2d knock-out mice had blindness in photoreceptor cells within the retina." (PMID 31105874, 2019).
Cerebral ischemia (1 paper, 2022). Restriction of arterial blood supply to the brain associated with insufficient oxygenation to support the metabolic requirements of the tissue. "In addition, in vitro experiments showed that miR-217 promotes the accumulation of histone deacetylase 5 (HDAC5) in the nucleus by targeting MEF2D, resulting in decreased expression of IL-10, thereby aggravating cognitive dysfunction after cerebral ischemia." (PMID 36399471, 2022).
craniosynostosis (1 paper, 2018). Craniosynostosis is defined as the premature fusion of one or more cranial sutures leading to secondary distortion of skull shape resulting in skull deformities with a variable presentation. "Out of seven genes with a high (< 10%) or moderate (< 25%) HI score (NES, CCT3, MEF2D, LAMTOR2, ETV3, SSR2, NTRK1), none of them have been linked to craniosynostosis." (PMID 29845577, 2018).
Down syndrome (1 paper, 2021). "Here, we uncovered that dual‐specificity tyrosine phosphorylation regulated kinase 1A (DYRK1A), a kinase critical in Down's syndrome pathogenesis, directly bound to and phosphorylated MEF2D at Ser251 in vitro." (PMID 34109727, 2021).
glioblastoma (1 paper, 2021). The most malignant astrocytic tumor (WHO grade IV). "We then examine MEF2D expression in glioblastoma cell lines." (PMID 34109727, 2021). "The kinase activity of DYRK1A may also be induced by MEF2D in glioblastoma cell lines." (PMID 34109727, 2021).
head and neck malignant tumors (1 paper, 2025). "In head and neck malignant tumors, overexpression of HDAC9 promotes carcinogenesis by targeting the transcription factor MEF2D and the proapoptotic MEF2 target, NR4A1/Nur77." (PMID 40145017, 2025).
hearing loss (1 paper, 2020). "Hence, our data suggest that the ribbon synapses may be regulated by FGF22/calcium/CalN/MEF2D signaling, which implied novel therapeutic targets for hearing loss." (PMID 32271716, 2020).
Insulin resistance (1 paper, 2025). Increased resistance towards insulin, that is, diminished effectiveness of insulin in reducing blood glucose levels. "TFs, such as Mef2d, which regulates mitochondrial biogenesis, and Suz12, which is involved in inflammatory gene regulation, provide molecular links to systemic glucose dysregulation and insulin resistance." (PMID 40076622, 2025).
ischaemic stroke (1 paper, 2021). "In view of the key role of MEF2D in neuroprotection and the correlation between nerve injury and prognosis in patients with ischaemic stroke, we studied the specific function of MEF2D in ischaemic cerebral stroke in rat model of I/R injury." (PMID 33621420, 2021).
malignant glioma (1 paper, 2019). A grade III or grade IV glioma arising from the central nervous system. "MEF-2D also acts as a potential oncogene in the tumorigenesis of malignant glioma and is highly upregulated in grade 3 and 4 malignant glioma patients." (PMID 31105874, 2019).
neuroendocrine carcinoma (1 paper, 2024). A malignant neuroendocrine neoplasm composed of cells containing secretory granules that stain positive for NSE and chromogranin. "This screen successfully identified small molecules that positively or negatively alter the splicing levels of the screen-assayed Mef2d microexon, as well as of a broader programme of neural microexons that is disrupted in ASD and activated in neuroendocrine cancers." (PMID 39068192, 2024).
oral squamous cell carcinoma (1 paper, 2019). "Overexpression of HDAC9 has been linked to poor prognosis of oral squamous cell carcinoma by targeting MEF-2D and repressing expression of MEF-2-dependent genes." (PMID 31105874, 2019).
periodontitis (1 paper, 2025). An acute or chronic inflammatory process that affects the tissues that surround and support the teeth. "Transcription factors such as Rela and Mef2d emphasize the molecular link between periodontitis and CVD." (PMID 40076622, 2025). "Given that periodontitis is characterized by chronic inflammation and bacterial infection, it is plausible that Mef2d may play a similar role in its pathogenesis." (PMID 40076622, 2025).
serous ovarian cancer (1 paper, 2017). "Using publicly available data, we also identified associations between greater MEF2D expression and shorter PFS in women with serous ovarian cancer." (PMID 29029385, 2017). "The Kaplan-Meier plotter (KM-plot) web-based application was used to assess associations between MEF2D and ZNF100 expression and outcome using data available from serous ovarian cancer patients." (PMID 29029385, 2017).
soft tissue sarcoma (1 paper, 2025). A malignant neoplasm arising from muscle tissue, adipose tissue, blood vessels, fibrous tissue, or other supportive tissues excluding the bones. "TCGA dataset in soft tissue sarcoma showed that PGAM2 expression positively correlates with MEF2A and MEF2D expression." (PMID 40707487, 2025).
Stroke (1 paper, 2021). Sudden impairment of blood flow to a part of the brain due to occlusion or rupture of an artery to the brain. "Given the key role of hippocampal tissue damage in the prognosis of stroke, we focused in this study on MEF2D and found that its level significantly reduced in hippocampal tissue in the CA1 area of the brain exposed to I/R." (PMID 33621420, 2021). "Next, MEF2D expression following stroke was evaluated by co‐staining MEF2D with PI in the hippocampus." (PMID 33621420, 2021).
subarachnoid hemorrhage (1 paper, 2025). A serious neurological disorder characterized by intracranial hemorrhage into the subarachnoid space. "Additionally, MB reduces neuroinflammation after subarachnoid hemorrhage via the Akt/GSK-3β/MEF2D signaling pathway." (PMID 39957615, 2025).
temporal lobe epilepsy (1 paper, 2024). A localization-related (focal) form of epilepsy characterized by recurrent seizures that arise from foci within the temporal lobe, most commonly from its mesial aspect. "We cannot rule out the possibility that MEF2D is crucial to refine the proper levels of BDNF, as abnormally increased levels of BDNF have been observed in the hippocampus and cortex of patients with temporal lobe epilepsy." (PMID 38796067, 2024).